TNF (tumor necrosis factor)
Diseases named in the same sentence as TNF in open-access papers (continued):
Sharing a sentence is not in itself a finding about the gene and the disease.
periodontitis (continued). "Within the periodontium, IL-1, IL-6, and TNF-α levels are enhanced in patients with both DM and periodontitis compared to patients with periodontitis alone and there is a direct relationship between cytokine levels and glucose control." (PMID 35052857, 2022). "This study showed that topical application of a mucosal adhesive gingival patch loaded with nano-emulsion of mangosteen rind extract has therapeutic potential in periodontitis by decreasing the expression of TNF-α and RANKL and increasing IL-10 expression." (PMID 36050950, 2022). "The pro-inflammatory cytokines TNF-α, IL-1β, and IL-6 play key roles in the occurrence and development of periodontitis." (PMID 36546940, 2022). "In the pregnant gingivitis and periodontitis groups, saliva TNF-α levels were shown to be significantly lower than in their control counterparts." (PMID 36432584, 2022). "HDAC9 RNA expression levels appear to be significantly increased in PDL stem cells under inflammatory conditions driven by periodontitis or exposure to TNFα, which impaired osteogenic capacity in vitro." (PMID 36291079, 2022). "P. gingivalis can promote the expression and secretion of different interleukins, like IL-8 and TNFα, which also contribute to the progression of periodontitis." (PMID 35978839, 2022). "We found that the mRNA expression of IL-1β, IL-6, and TNF-α in the periodontitis group was, respectively, 2.59-, 5.23-, and 2.29-fold than that of the control group." (PMID 35340409, 2022). "TNF-α plays a vital function in progressing periodontitis by increasing the production of matrix metalloproteinases, thereby leading to periodontal destruction." (PMID 35336824, 2022). "For the M1 phenotype, levels of TNF-α and IL-6 increased following exposure to periodontitis saliva, but this increase was significantly reduced by treatment with G3@SeHANs and PAMAM-G3." (PMID 36207325, 2022). "We also found serum from periodontitis patients had a smaller effect on TNF-α and IL-6 levels than saliva." (PMID 36207325, 2022). "LPS lead to the dysregulation of host immuno-inflammatory response and the release of a large number of inflammatory factors, such as TNF-α and IL-1β, which eventually result in periodontitis." (PMID 35464198, 2022). "TNF-α, IL-1β, and IL-6 levels in the gingival crevicular fluid of patients with periodontitis are significantly higher than those in healthy individuals, and these cytokines decreased significantly after treatment." (PMID 36546940, 2022). "The expression of TNF-α and IL-6 in the gingival tissues of experimental rats treated with curcumin was significantly lower than the experimental periodontitis animal." (PMID 35903322, 2022). "In a ligature-induced periodontitis rat model, mRNA levels of inflammatory cytokines such as IL-6, IL-1β, TNF-α, RANKL, and OPG were increased within the first week of inducing the disease." (PMID 35628390, 2022). "Periodontitis is an inflammatory disease that mainly has bacterial etiology, where immune cells secreting pro-inflammatory cytokines such as IL-1, TNF, and IL-33, which contribute to tissue damage, are invoked." (PMID 36362030, 2022). "The results showed that patients with periodontitis presented significantly more inflammatory mediators, such as TNF-α, IL-6, IL-8, ADMA, Galectin-3, in comparison with healthy subjects." (PMID 35473620, 2022). "A mucoadhesive gingival patch with nano-emulsion of mangosteen rind extract has the potential to treat periodontitis by decreasing TNF-α, RANKL, and increasing IL-10 expression." (PMID 36050950, 2022). "TNF-α and IL-6 are the commonly found bone resorption-related factors and inflammatory cytokines during periodontitis." (PMID 36053353, 2022). "In contrast, IL-6, IL-1β, and TNF-α exhibited strong staining in the periodontitis group, suggesting that the periodontitis model had been well established." (PMID 35340409, 2022).
periodontitis (continued). "Our results indicated that DhHP-6 has therapeutic effects in periodontitis by reducing the levels of the inflammatory factors TNF-α and IL-1β in HGFs sensitized by LPS and reducing the cellular inflammatory response." (PMID 36546940, 2022). "Interleukin-1β (IL-1β) and tumor necrosis factor-α (TNF-α) are important cytokines in periodontitis, and their concentrations in GCF are higher with periodontitis." (PMID 35186787, 2022). "Secondly, although TNFα are the main pro-inflammatory cytokines in experimental periodontitis model, other cytokines such as IL-6 and INF-γ must be studied with PPARα activation in the future." (PMID 35830121, 2022). "Apart from IL-6, TNF-α is a typical inflammatory cytokine in periodontitis that directly stimulates osteocytes to produce RANKL and induce osteoclastogenesis or promote sclerostin expression in osteocytes leading to increased osteoclastogenesis." (PMID 35628348, 2022). "It has been reported that TNF-α, IL-1β, IL-6, and IL-17 are highly expressed in periodontal tissues such as periodontal membranes of patients with chronic periodontitis as the expression level increases with the increase of inflammation." (PMID 35942384, 2022). "Systemic inflammation, indicated by elevated levels of TNFα, IL-1β, IL-6, and IFNγ in the serum, is clinically present in patients with periodontitis." (PMID 35874771, 2022). "The findings of this study demonstrated that following treatment, the expression levels of inflammatory mediators (RANKL, TNF-α) decreased in the periodontal tissues in which periodontitis was induced by injection of P. gingivalis." (PMID 36050950, 2022). "One of them assessed the DNA methylation of the TNF gene promoter region, demonstrating the hypermethylation of over 12 dinucleotides of CpG during periodontitis." (PMID 36233348, 2022). "Osteoclasts and expression levels of TNF-α and IL-1β were significantly increased in periodontal tissues of mice receiving periodontitis patients donated microbiome compared to these transplanted with healthy subjects donated microbiome." (PMID 35958276, 2022). "Elevated systemic inflammatory cytokines, such as Interleukin-1β (IL-1β), Interleukin-6 (IL-6), C-Reactive protein (CRP), and Tumor necrosis factor-α (TNF-α), were attributable to periodontitis have been documented by previous studies." (PMID 35162556, 2022). "Spearman's test was done to examine the correlation between TNF-α level and severity of periodontitis in diabetics." (PMID 35016229, 2022). "Periodontitis TNF-α is a proinflammatory cytokine whose sources are neutrophils, monocytes, and macrophages." (PMID 35178093, 2022). "Members of the IL-1, IL-6, and TNF families are key proinflammatory cytokines involved in periodontitis." (PMID 35845957, 2022). "Periodontitis causes an increase in the salivary-soluble TNF-α receptor, which leads to an increase in the TNF-α level." (PMID 35877392, 2022). "In periodontitis, inflammation-inducing factors, such as TNF-α, IL-1β, and IL-6, are secreted from PDL cells due to bacterial endotoxin release, causing periodontal inflammation and infection." (PMID 36145616, 2022). "Two pivotal inflammatory mediators in thyroid disorders, IL-6 and TNF-α, also play a role in inflammation and tissue destruction in periodontitis." (PMID 36359775, 2022). "A recent study demonstrated that periodontitis enhanced the levels of proinflammatory cytokines (TNF-α and IL-1β), oxidative stress (MDA), and proteases (MMP-8, MMP-9, and cathepsin D) in rat kidneys, while melatonin suppressed them significantly." (PMID 36498871, 2022). "Here, we selected TNF-α to mock the microenvironment of periodontitis, and we established a TNF-α concentration gradient to explore biological behaviors of inflammatory PDLSCs." (PMID 36199627, 2022). "Immunocompetent cells secrete pro-inflammatory cytokines like TNF-α into marginal tissues affected by periodontitis." (PMID 35137648, 2022).
periodontitis (continued). "Proinflammatory cytokines, such as IL-1β, IL-6, and TNF-α, have been used as biomarkers to identify periodontitis and peri-implantitis." (PMID 34931168, 2021). "Neutrophils in periodontitis also have a higher cytokine reactivity as the expression of chemokines and the release of cytokines (IL-1β, IL-6, IL-8, and TNF-α) are higher in neutrophils isolated from late-onset periodontitis patients." (PMID 33777839, 2021). "This indicated ELAVL1 andCBLL1 played an important role in TNF or cytokine reactions in periodontitis." (PMID 33724691, 2021). "Pro-inflammatory cytokines such as IL-1β, TNF-α and IL-6 are produced by monocytes, and macrophages and play a critical role in the pathogenesis of periodontitis." (PMID 34481488, 2021). "Our results show that the macrophage-specific Act1 knockdown aggravates periodontitis possibly via activation of TNF/NF-κB signaling." (PMID 33748112, 2021). "GCF from periodontitis patients had significantly higher concentrations of TNF-α, CCL2, IL-6, IFN-γ, and CXCL8 than controls." (PMID 34502071, 2021). "Periodontitis is associated with increased serum levels of C-reactive protein (CRP) and pro-inflammatory cytokines (e.g., tumor necrosis factor-α), as well as decreased anti-inflammatory markers (e.g., interleukin-10)." (PMID 34769677, 2021). "Another study demonstrated a co-occurrence of both elevated IL-12 and TNF-α in local lesions of gingivitis and chronic periodontitis compared to periodontal healthy subjects." (PMID 34199238, 2021). "Macrophage polarization toward a higher M1/M2 ratio was shown to be involved in the progression of gingivitis to periodontitis, with sustained IL-1β, IL-6, and TNF-α and diminished IL-10 expression." (PMID 34063147, 2021). "Next, we compared the TNF-α secretion in OBMCs obtained from healthy individuals and periodontitis patients." (PMID 33672708, 2021). "The proportion of TNF-α- or IL-17-producing γδ T cells were significantly elevated in the regional lymph nodes of a HFD-fed mice with periodontitis." (PMID 35069547, 2021). "Human studies have demonstrated that patients suffering from periodontitis exhibit higher concentrations of proinflammatory cytokines, such as tumor necrosis factor-alpha (TNF-α), C-reactive protein (CRP), interleukin-6 (IL-6) and Il-1β." (PMID 33804123, 2021). "In vivo, BAFF blockade decreased the levels of TNF-α in the periodontium in a ligature-induced mouse periodontitis model." (PMID 34481478, 2021). "In periodontitis animal models, anti-TNF treatment can reduce inflammatory cell recruitment and bone loss." (PMID 33778080, 2021). "An interesting trial compared periodontal condition in patients with RA and periodontitis before and after biological therapy in two cohorts: one under tocilizumab and the other receiving medication with TNF inhibitors." (PMID 33672771, 2021). "As expected, induction of periodontitis led to the increased TNF and IL-6 expression in the gingival tissues." (PMID 34899728, 2021). "Rats with periodontitis (group 3) expressed significantly higher immunoreactivities of IL-6 and TNF-α and lower IL-10 immunoreactivity compared to those other groups (p<0.05)." (PMID 34586188, 2021). "TNF-α’s mean concentration was the highest in patients with moderate periodontitis (5.41 ± 2.12 pg/mL) and significantly greater than in GCF of healthy subjects (p = 0.025)." (PMID 33726736, 2021). "TNF-α is also a pro-inflammatory cytokine that is involved in inflammatory diseases, including rheumatoid arthritis, inflammatory bowel disease, and periodontitis." (PMID 33673606, 2021). "The TNF-α level in PISF in patients with implants was markedly higher compared to subjects with healthy periodontium or patients with mild periodontitis." (PMID 33726736, 2021). "At the site of periodontitis, the levels of proinflammatory cytokines such as TNF-α, IFN-γ, IL-1, IL-6, IL-12 and G-CSF are significantly increased while anti-inflammatory cytokines are decreased (IL-4 and IL-10)." (PMID 34868054, 2021).
periodontitis (continued). "Since LL-37 exerts bactericidal and anti-inflammatory activities by binding to LPS, the degradation of this peptide also abolishes its anti-inflammatory effect and promotes the release of TNF-α, contributing to the development of late-onset periodontitis." (PMID 33777839, 2021). "Pro-inflammatory cytokines (such as IL-1 and TNF) lead to periodontitis while anti-inflammatory cytokines ameliorate the disease." (PMID 34868054, 2021). "Here, we show that preconditioning of gingival tissue-derived MSCs (GMSCs) with tumor necrosis factor-alpha (TNF-α) is ideal for the treatment of periodontitis." (PMID 33359765, 2021). "In the study conducted by Chen, it was indicated that TNF-α participates in the pathogenesis of periodontitis." (PMID 34064286, 2021). "Further blood analysis revealed that the experimental periodontitis mice had elevated LPS levels (P <0.05), while changes in inflammatory factors IL-6 and TNF-α were consistent with LPS." (PMID 35118014, 2021). "The ratio of RANKL/OPG is modulated mainly by tumor necrosis factor (TNF) and interleukin-1 (IL-1) released from host cells, subsequently activating osteoclasts, resulting in periodontitis." (PMID 33671221, 2021). "AT1 knockout mice submitted to ligature-induced periodontitis (AT1-L) had much lower levels of TNF-α in gingival tissue when compared to WT-L and AT2-L, both submitted to periodontitis (p < 0.001)." (PMID 34884653, 2021). "In periodontitis, there is a local increase in the concentration of inflammatory mediators (IL-1, IL-6, and TNF-α), which not only have a destructive effect on the periodontium but can also initiate the formation of atherosclerotic plaque." (PMID 33477706, 2021). "As a key molecule involved in the induction and maintenance of inflammation, TNF-α induces local inflammation, resulting in bone destruction in RA and periodontitis by enhancing the receptor activator of nuclear factor kappa-B ligand (RANKL) expression." (PMID 33716675, 2021). "We found that the GCF samples obtained from periodontitis patients contained significantly higher proportions of cytokines such as TNF-α, CCL2, IL-6, IFN-γ, and CXCL8 compared to the samples obtained from systemically and periodontally healthy controls." (PMID 34502071, 2021). "In patients with periodontitis, inflammatory markers (IL-6, IL-10, TNF-α, C-reactive protein, and ALP) in the gingival crevicular fluid are increased and directly correlated with the severity of the disease." (PMID 33430249, 2021). "The reports from the literature and results of this study indicate the role of macrophage-specific Act1 on the pathophysiology of periodontitis possibly via TNF/NF-κB signaling-mediated M1 macrophage polarization." (PMID 33748112, 2021). "Here, the serum‐based three different cytokines (IL‐1β, IL‐6, TNF‐α) showed up‐regulated expression in periodontitis, which were consistent with previous studies." (PMID 34272761, 2021). "Our results indicated that the superposition of periodontitis and hypertension significantly upregulated IL‐1 β, TNF‐α, and F4/80, which is consistent with the pathological manifestations of glomerular mesangial dilation and tubulointerstitial fibrosis." (PMID 33448153, 2021). "Surprisingly, salivary levels of TNF-α, IL-6, IL-8, and IL-17A can be affected not only by periodontitis but also in RA." (PMID 33672771, 2021). "Soluble protein delivery of a TNF-α antagonist inhibits alveolar bone resorption induced by periodontitis." (PMID 34868054, 2021). "We have established that TNF-α concentration was remarkably higher in patients with implants than subjects with healthy periodontium and patients with mild periodontitis." (PMID 33726736, 2021). "Several studies have indicated elevated levels of TNF-α in patients with periodontitis, peri-implant disease, oral squamous cell carcinoma, and oral candidiasis." (PMID 34829612, 2021).
periodontitis (continued). "Increase of such proinflammatory cytokines as: IL-1α, IL-1β, TNF-α, IL-6, and IL-17 were shown in patients with acute or chronic periodontitis." (PMID 33467650, 2021). "In chronic periodontitis, the nuclear expression of TNF- α, IL-1b, and IL-8 is significantly up-regulated following NF-kB activation." (PMID 34299815, 2021). "It is observed that inflammatory responses are inhibited by the antagonist of IL-1 and TNF-α, thereby decreasing the amount of bone destruction in experimentally induced periodontitis." (PMID 34770985, 2021). "Periodontitis is characterized by an elevated pro-inflammatory: anti-inflammatory ratio, with increased levels of cytokines such as IL-1β, IL-6 and TNF-α." (PMID 34630089, 2021). "Inflammatory mediators, including TNF-α, are induced in chronic inflammatory conditions such as periodontitis and gingivitis." (PMID 34299679, 2021). "In periodontitis, proinflammatory cytokines, such as IL-1β, IL-6, IL-8, and TNF-α, seem to be the major mediators, involved in the destruction of periodontal tissue." (PMID 34035660, 2021). "Its expression is closely correlated with proinflammatory cytokines production (TNF-α and IL-1β) and with clinical conditions of periodontitis." (PMID 34566966, 2021). "In obese rats, adipose tissue inflammation was significantly aggravated by periodontitis with an increased expression of pro-inflammatory cytokines such as Interleukin-6 (IL-6) and Tumor Necrosis Factor α (TNF-α)." (PMID 33919425, 2021). "The most established cytokines in periodontitis patients in this regard are IL-1α, IL-β, IL-6, IL-8, and TNF-α." (PMID 34207600, 2021). "Gipr-knockout mice with ligature-induced periodontitis also showed a significant increase in the gene expression of gingival inflammatory cytokines, TNF-α, and inducible nitric oxide synthase (iNOS), as compared to WT mice with experimental periodontitis." (PMID 34445604, 2021). "Apical periodontitis patients were treated with anti-TNF-α biologic medications and showed faster healing than the controls." (PMID 35046930, 2021). "In AD model rats with induced periodontitis, compared to controls, TNF-α levels were significantly higher in the hippocampus, IL-1 levels were higher in the cerebral cortex, and IL6 levels were higher both in the hippocampus and cerebral cortex." (PMID 34769677, 2021). "Macrophage infiltration, levels of inflammatory cytokines such as IL-6, IL-1β, and TNFα, and M1 macrophage polarization were enhanced in anti-Act1 periodontitis mice compared to wildtype periodontitis mice." (PMID 33748112, 2021). "Patients with chronic periodontitis have elevated levels of proinflammatory mediators, including TNF-α, IL-1, and IL-6 in gingival crevicular fluid, even in the absence of other chronic systemic diseases." (PMID 34043630, 2021). "From the immunological point of view, BBR by attenuating the production of TNF‐α and IL‐17, as well as the number of IL‐17A+ cells in the alveolar bone effectively inhibited the local and systemic inflammation in the periodontitis rat model." (PMID 34719112, 2021). "The concentration of IL-1β, IL-6, and TNF-α was significantly higher in periodontitis patients than in healthy volunteers (P < 0.05)." (PMID 34592963, 2021). "In periodontitis, TNF-α was involved in immunoregulatory and inflammatory processes that recruits neutrophils and other leukocytes to the inflammation site." (PMID 33861790, 2021). "In particular, ginsenosides inhibited the release of the pro-inflammatory cytokines, TNF-α and IL-6, which are important inflammatory factors in periodontitis." (PMID 33917440, 2021). "Together with IL-1β, TNF-α has been extensively studied in relation to periodontitis as a pro-inflammatory and immunomodulatory cytokine." (PMID 34408814, 2021).